SOCS1 (suppressor of cytokine signaling 1)
Diseases named in the same sentence as SOCS1 in open-access papers (continued):
Sharing a sentence is not in itself a finding about the gene and the disease.
pancreatic cancer (23 papers, 2003 to 2025). "This notion is supported by current findings that pancreatic tumor cells are able to induce DNA methylation of the suppressor of cytokine signaling 1 (SOCS1) gene in cancer-associated fibroblasts (CAFs), and these epigenetically-regulated CAFs potentially promote the growth of tumor cells in vivo." (PMID 28383487, 2017). "Therefore, miR-155 regulation of SHIP-1 and SOCS1 expressions may be potential biomarkers and therapeutic targets for the treatment of pancreas-associated diseases (i.e., pancreatitis and pancreatic cancer)." (PMID 35892872, 2022). "MiR-155 also increases proliferation and invasion in pancreatic cancer cells by inhibiting the suppressor of cytokine signaling 1 (SOCS1)." (PMID 38559560, 2024). "For instance, Suppressor Of Cytokine Signalling 1 (SOCS1) had a recurrent element in its proximal promoter in prostate, colorectal and pancreatic cancer samples (FDR < 0.00225)." (PMID 34282050, 2021). "Correlation analyses revealed a strong positive correlation between SOCS1 and Foxp3 in the cachectic pancreatic cancer patients." (PMID 34900737, 2021). "5-Aza-2′-deoxycytidine treatment of the SOCS-1-methylated pancreatic cancer cell lines led to restoration of SOCS-1 gene expression." (PMID 12865927, 2003). "In this study, we demonstrate that SOCS-1 is a frequent target for aberrant methylation in pancreatic cancer." (PMID 12865927, 2003). "In conclusion, SOCS-1 is commonly methylated in pancreatic adenocarcinoma and loss of SOCS-1 in pancreatic cancer is moderately associated with increased IL-6-mediated growth." (PMID 12865927, 2003). "In this study, we determined the prevalence and significance of SOCS-1 methylation in pancreatic neoplasms." (PMID 12865927, 2003). "Moreover, there is a significant correlation among SOCS1 and Foxp3 protein in cachectic patients with pancreatic cancer." (PMID 34900737, 2021). "In pancreatic cancer patients, a significant negative association was recorded between serum SOCS1 and Foxp3 with the presence of cachexia." (PMID 34900737, 2021). "Furthermore, we demonstrated that IL-6 induced modest increases in cell proliferation only in pancreatic cancer cells (PL10) harbouring methylated SOCS-1 gene." (PMID 12865927, 2003). "To investigate whether the suppression of SOCS-1 gene expression was mediated by methylation of CpG islands in human pancreatic cancer cells, we treated the pancreatic cancer cell lines PL10 and PL12 cells with 5-Aza-dC." (PMID 12865927, 2003). "Aberrant methylation in the CpG island of the SOCS-1 gene was detected in six of 19 (31.6%) human pancreatic cancer cell lines using methylation-specific PCR, and was associated with a loss or reduction of gene expression in five of the six methylated cell lines." (PMID 12865927, 2003). "We also demonstrate that silencing of SOCS-1 gene expression occurs in pancreatic cancer cell lines harbouring methylated SOCS-1 and such silencing could be restored after 5-Aza-dC treatment, indicating that methylation was the likely mechanism by which the SOCS-1 gene expression was suppressed." (PMID 12865927, 2003). "Downregulation of SOCS-1 by gene promoter hypermethylation has been recently reported in 65% of HCC cell line, 62.9% of multiple myeloma patients samples and 31.6% of pancreatic cancer cell lines with resultant activation of STAT3." (PMID 15354212, 2004). "Since SOCS-1 methylation is only found in a subset of pancreatic adenocarcinomas, its utility as a diagnostic marker would only be as part of a panel of other aberrantly methylated genes that are specifically methylated in pancreatic cancer but not in normal pancreas." (PMID 12865927, 2003). "Pancreatic cancer cell migration, invasion and metastasis can be regulated by miR-155 via targeting 53-induced nuclear protein 1 (TP53INP1) or by regulating the suppressor of cytokine signaling 1 (SOCS1) through the STAT3 signaling pathway." (PMID 27240340, 2016).
pancreatic cancer (continued). "Thus, the interaction of PDAC cells with CAFs induces in these cells the methylation of some genes and, notably, of SOCS1; the inhibition of SOCS1 in fibroblast cells activates STAT3 and induces the release of insulin-like growth factor-1, required to sustain the growth of pancreatic cancer cells." (PMID 29156578, 2017). "In contrast, in this study we found that PanINs lacked methylation of SOCS-1 suggesting that if loss of SOCS-1 is a selected event, it does not provide a selective advantage to a pancreatic neoplasm until the neoplasm has evolved into an invasive adenocarcinoma." (PMID 12865927, 2003).
atherosclerosis (17 papers, 2012 to 2025). A disease characterized by the build-up of fatty material and calcium deposition in the arterial wall resulting in partial or complete occlusion of the arterial lumen. "Loss of SOCS-1 in the low-density lipoprotein receptor deficient murine model of atherosclerosis resulted in a complex, systemic and ultimately lethal inflammation with increased generation of Ly-6Chi monocytes and activated macrophages." (PMID 23300554, 2012). "MiR‐155 can also reduce inflammation status by targeting SOCS1, while decreased miR‐155 levels can inhibite the formation of atherosclerosis." (PMID 39495676, 2024). "Over-expression of miR-155 promotes the formation of foam cells and aggravates atherosclerosis by targeting SOCS1 via STAT3 and NF-κB signaling pathway." (PMID 34150863, 2021). "MicroRNA-155-5p promotes progression of atherosclerosis mainly by enhancing inflammatory response during the development of the disease by targeting SOCS1 via the STAT3 and NF-κB signaling pathways." (PMID 34150863, 2021). "More specifically, mRNA targets such as Bcl6, Hbp1, Mst2, and Socs1, which are reduced in atherosclerosis have been shown to play a protective role against the disease’s development." (PMID 30369883, 2018). "In summary, this study demonstrates the athero-protective nature of SOCS-1 in experimental, murine atherosclerosis." (PMID 23300554, 2012). "Overall, data indicate that compounds mimicking SOCS1 could be valuable therapeutics in atherosclerosis." (PMID 32824091, 2020). "SOCS-based strategies to impair pathological JAK/STAT activity were already reported for the treatment of cardiovascular diseases confirming the anti-inflammatory and atheroprotective properties of the SOCS1/SOCS3 gene delivery in experimental atherosclerosis models." (PMID 32824091, 2020). "In addition, it has been demonstrated that SOCS1 is a potent inhibitor of the IFNγ signaling pathway and can prevent atherosclerosis by inhibiting IFNγ signaling." (PMID 31024559, 2019). "Importantly, in this study, statistically significant inverse correlation between SOCS1 and miR-155 expression was observed indicating a significant biological function of SOCS1-miR-155 in atherosclerosis." (PMID 31703274, 2019). "Hence, the overexpression of miR-221-5p could promote the production of inflammatory cytokines and the progression of atherosclerosis through the inhibition of SOCS1." (PMID 37239987, 2023). "miR-155 also promotes atherosclerosis by suppressing the activity of anti-inflammatory factors, “HMG1 protein”, “B-cell lymphoma 6 (Bcl-6) protein”, and “suppressor of cytokine signaling 1 (SOCS1)”." (PMID 32937836, 2020). "In chronic inflammation settings, such as atherosclerosis, exercise-induced downregulation of miR-155 attenuates macrophage M1 polarization by relieving inhibition of SOCS1 (Suppressor of Cytokine Signaling 1), thereby favoring a shift toward the anti-inflammatory M2 phenotype." (PMID 40822014, 2025). "Interestingly, we found that PIAS3 expression, unlike SOCS1 expression, exhibits significant declines, even during the early stages of atherosclerosis." (PMID 27845432, 2016).
colon carcinoma (17 papers, 2011 to 2024). "Here, we investigated SOCS1 relevance for CRC by querying gene expression datasets of human CRC specimens from The Cancer Genome Atlas (TCGA), and by SOCS1 gain/loss-of-function analyses in murine and human colon carcinoma cells." (PMID 26391193, 2015). "Furthermore, SOCS1-regulated functions were investigated by gain- and loss-of-function studies in murine and human colon carcinoma cell models." (PMID 26391193, 2015). "The importance of SOCS1 for inhibition of inflammation-associated tumour development is supported by the finding that a strain of SOCS1−/− mice, in which SOCS1 expression is deleted in all types of cells except T and B cells, developed chronic colitis and colon tumours." (PMID 24757565, 2014). "A different team of researchers report that SOCS1 (suppressor of cytokine signaling 1) exerts a suppressor effect in a colon cancer line of cells via inhibition of EMT and the spread of tumor cells." (PMID 37373289, 2023). "According to our findings, MLH1-methylated CIMP-H CRC was significantly associated with high frequencies of a proximal colonic tumor location and RUNX3/SOCS1 promoter methylation compared with MLH1-unmethylated CIMP-H CRC." (PMID 26883113, 2016). "Colonic cancer HT-29 cells with high STAT6 expression phenotype (STAT6high) exhibited low constitutive expression of STAT6-negative regulators SOCS1 and SHP1 because of gene hypermethylation, with the opposite findings in STAT6null cells." (PMID 24757565, 2014). "This strongly suggests that chronic activation of the IFNγ-STAT1 pathway that occurs in the absence of SOCS1 causes colitis-induced colon tumours." (PMID 24757565, 2014). "The current study aimed to investigate the effect of valproic acid (VPA) on SOCS-1, SOCS-2, SOCS-3, SOCS-5, SOCS6, and SOCS-7 gene expression and cell growth inhibition in colon carcinoma IS1, IS2, and IS3 cell lines." (PMID 35611249, 2022). "Previously, we reported that valproic acid upregulated SOCS-1 and SOCS-3 gene expression in colon carcinoma SW48 cell line." (PMID 35611249, 2022). "Previously, we reported that the histone deacetylase inhibitor valproic acid can reactivate silenced SOCS-1 and SOCS-3, resulting in apoptosis induction in the colon carcinoma SW48 cell line." (PMID 35611249, 2022). "The histone deacetylation of SOCS-1 and SOCS-3 has been indicated in colon cancer, and that of SOCS1 has been indicated in human cervical carcinoma cell lines HeLa, CaSki, and SiHa." (PMID 35611249, 2022). "Inconsistently, our previous work indicated that valproic acid and zebularine can up-regulate SOCS-1 and SOCS-3 gene expression leads to cell growth inhibition in the colon carcinoma SW48 cell line." (PMID 34319031, 2021). "To evaluate the functional relevance of SOCS1 in CRC cells, we have chosen to use the murine CT26 and CT36 colon carcinoma cell lines." (PMID 26391193, 2015). "Similar to SOCS1 and SHP1, STAT6high HT-29 cells expressed low constitutive mRNA of SOCS3 and SOCS7 than STAT6null colonic cancer Caco-2 cells." (PMID 24757565, 2014). "In total, 31 CpG sites, located in 8 different genes (RUNX3, MLH1, NEUROG1, CDKN2A, IGF2, CRABP1, SOCS1 and CACNA1G) were investigated in 64 distinct colon cancers and 2 colon cancer cell lines." (PMID 24466191, 2014). "The results of the current study demonstrate that VPA plays its role through the upregulation of SOCS-1, SOCS-2, SOCS-3, SOCS-5, SOCS6, and SOCS-7 genes, resulting in cell growth inhibition and apoptosis induction in colon carcinoma IS1, IS2, and IS3 cell lines." (PMID 35611249, 2022). "Furthermore, in colonic cancer cell line HT-29 that constitutively expresses STAT6, there is downregulation of CIS and SOCS7 (in addition to SOCS1, SOCS3, and SHP1)." (PMID 24757565, 2014).
colon carcinoma (continued). "Our study suggests that for the diagnosis of colon cancer, it is better to examine the expression status rather than the methylation status of IGF2, SOCS1, MLH1, and CACNA1G genes." (PMID 38874740, 2024).
liver cancer (17 papers, 2010 to 2026). An epithelial or non-epithelial malignant neoplasm that arises from the liver. "SOCS1 functions as a tumor suppressor in liver cancer and in many other cancers, but the underlying mechanisms are not yet completely understood." (PMID 38254783, 2024). "Moreover, loss of SPTBN1 expression induces liver cancer through downregulation of SOCS1 expression as well." (PMID 34527677, 2021). "In this study, we examined the role of SOCS1 in liver cancer cells exposed to chemicals that induce oxidative stress and carried out a proteomic study." (PMID 38254783, 2024). "SOCS1 alterations through SOCS7 and CISH alterations were detected in liver cancer tissues at the following frequencies: SOCS1, 1.1%; SOCS2, 0.8%; SOCS3, 6%; SOCS4, 0.3%; SOCS5, 1.3%; SOCS6, 1.3%; SOCS7, 2.4%; and CISH, 2.7%." (PMID 39307915, 2024). "This stress reduction pathway represents a potential therapeutic target in SOCS1-less liver cancers." (PMID 36765862, 2023). "Gene coding for the SOCS1 protein is frequently inactivated in liver cancer, suggesting that SOCS1 protects liver cells from becoming cancerous." (PMID 36765862, 2023). "Our findings on mouse models of liver cancer, and data from human liver cancer patients, show that SOCS1 suppresses the expression of CDKN1A, and in doing so, prevents the ability of liver cells to withstand the stress associated with cancer growth." (PMID 36765862, 2023). "Suppressor of cytokine signaling-1 (SOCS1) gene has been recognised as tumor suppressor gene and found to be related to lymphatic metastasis and disease progression of liver cancer." (PMID 35421941, 2022). "Importantly, epigenetic regulation of SOCS1 and subsequently ISGylation may be important factors in the development of cell type-specific host defense responses in hepatocytes, which could also be implicated in the development of liver cancer." (PMID 36439639, 2022). "Loss of SPTBN1 increases p65 protein stability via the inhibition of SOCS1 and enhances NF-κB activation, stimulating inflammatory responses and immune-suppressive conditions for the formation and progression of liver cancer." (PMID 33754058, 2021). "Based on the downregulation of SOCS1 expression in liver cancer specimens from the Oncomine database and the detection of SOCS1 in primary clinical specimens, we propose that SOCS1 plays an important role in the occurrence and development of HCC." (PMID 32096766, 2020). "The constitutive activation of STAT3 in liver cancer is frequently due to the aberrant methylation and silencing of Suppressor of Cytokine signaling-1 (SOCS-1) and -3 (SOCS-3)." (PMID 20712901, 2010). "Understanding how the SOCS1 protein protects from liver cancer could help in the development of new treatment strategies." (PMID 36765862, 2023). "This notion is supported by the increased susceptibility of mice lacking SOCS1 to develop liver cancer." (PMID 36765862, 2023). "In the progression of liver cancer, c-Met is regulated by various factors such as miRNAs and SOCS1." (PMID 32117981, 2020). "Inhibits the expression of SOCS1 and PDCD4, enhancing immune evasion mechanisms, promoting liver cancer cell growth." (PMID 39911396, 2025). "Additional studies on SOCS1 expression and the ISGylation system, in HCC, may clarify the mechanisms underpinning their roles in the development of liver cancer, which may differ between the pre-malignant and malignant states." (PMID 36439639, 2022).
rheumatoid arthritis (17 papers, 2004 to 2026). A chronic, systemic autoimmune disorder characterized by inflammation in the synovial membranes and articular surfaces. "The journal retracts the article titled, "Rheumatoid Arthritis-Associated MicroRNA-155 Targets SOCS1 and Upregulates TNF-α and IL-1β in PBMCs" [...]." (PMID 42007900, 2026). "In Rheumatoid Arthritis (RA), aberrant upregulation of SOCS1 and SOCS3 has been documented in peripheral blood T lymphocytes, monocytes, and synovial tissues, with expression levels correlating with disease activity and progression." (PMID 41393140, 2025). "The elevated level of miR-155 correlates with the upregulation of TNF-α and the downregulation of SOCS1 in rheumatoid arthritis." (PMID 35563301, 2022). "Genes showing lower levels of expression in AD included ICAM-1, IL-1B, CCR1, IFIH1, SOCS1, TNFAIP3 and TNFSF13B, which are strongly associated with acute and chronic inflammation and adult rheumatoid arthritis." (PMID 26310571, 2015). "We also demonstrated the significantly lower SOCS1 expression and higher NO production in MSCs isolating from rheumatoid arthritis patient." (PMID 24826993, 2014). "Interestingly, this putativeimmuno-receptor, which belongs to a gene complex involving CIITA and SOCS1, islinked to autoimmune disorders such as multiple sclerosis and rheumatoid arthritis." (PMID 25520755, 2014). "Additionally, we found the significantly lower SOCS1 expression and higher nitric oxide (NO) production in MSCs isolated from synovial fluid of rheumatoid arthritis patients." (PMID 24826993, 2014). "LINC-PINT is downregulated in rheumatoid arthritis (RA) tissues and TNF-α stimulated RA cells, increasing SOCS1 expression by inhibiting the activation of the ERK signaling pathway in RA synovial fibroblasts induced by TNF-α by sponging miR-155-5p." (PMID 37553573, 2023).
acute myeloid leukemia (16 papers, 2013 to 2025). Acute myeloid leukemia (AML) is a group of neoplasms arising from precursor cells committed to the myeloid cell-line differentiation. "SOCS1 is commonly silenced by hypermethylation and occasionally mutated in acute myeloid leukemia (AML)." (PMID 26788993, 2016). "Research has also shown that SOCS1 gene was commonly silenced by hypermethylation (and occasionally mutation) in acute myeloid leukemia (AML) and that its reintroduction had caused growth suppression in affected cells." (PMID 24757565, 2014). "It was reported that Gfi1 transcriptionally suppressed SOCS1 expression in acute myeloid leukemia cells and promoted the proliferation and migration of esophageal squamous cell carcinoma cells through restraining SOCS1." (PMID 40787173, 2025). "There is a close relationship between UNC93B1, IL2RA, HSPA1B, and SOCS1 overexpression and chemotherapy resistance in patients with acute myeloid leukemia (AML)." (PMID 39213256, 2024). "In patients with acute myeloid leukemia, SOCS1 expression is negatively correlated with mutant CEBPA." (PMID 36832783, 2023). "Downregulation of suppressor of cytokine signalling-1 (SOCS1) is one of the vital reasons for JAK1-STAT3 pathway activation in acute myeloid leukaemia (AML)." (PMID 29991678, 2018). "SOCS1 gene methylation has been reported to cause gene silencing which is accompanied by downstream JAK/STAT signaling and promotion of cell proliferation in acute myeloid leukaemia." (PMID 35421941, 2022). "SOCS-1 hypermethylation, for example, has been identified in acute myeloid leukemia and MDS, and patients with ET and PV have similar abnormalities in the SOCS-1 or SOCS-3 genes." (PMID 40699626, 2025). "AKR1C2 combined with SOCS1 could exert synergistic effects on predicting the prognosis in patients with acute myeloid leukemia (AML)." (PMID 36701414, 2023). "Considering the high expression of SOCS1 in mregDCs, genetically modified DCs with SOCS1 silencing were evaluated (NCT01956630) and were found to elicit powerful immune effects and increase the survival of patients with acute myeloid leukaemia." (PMID 36808888, 2023).